OTULINL (OTU deubiquitinase with linear linkage specificity like)
Description:
Lacks deubiquitinase activity.
Synonyms: FAM105A; FLJ11127; NET20
Tractability: Antibody: UniProt places it where antibodies can reach, with high confidence. PROTAC: ubiquitination databases record sites on it.
Gene: Protein-coding gene on chromosome 5 (14,581,792 to 14,616,180, forward strand). Ensembl gene ENSG00000145569.
Subcellular location: Cytoplasm; Endoplasmic reticulum membrane; Nucleus envelope
Subcellular location (Human Protein Atlas): Cytosol; Nucleoli
Gene Ontology:
Molecular function: protein binding; ubiquitin binding; ubiquitin-like protein peptidase activity
Biological process: protein deubiquitination
Cellular component: cytoplasm; cytoplasmic side of endoplasmic reticulum membrane; endoplasmic reticulum membrane; nuclear envelope
Genetic constraint (gnomAD): Loss-of-function variants: 43 observed, 45.76 expected, observed/expected ratio (o/e) 0.94, 90% interval 0.74 to 1.21. The upper end of that interval is the gene's LOEUF score, 1.21, which puts it in group 5 of 6, group 1 being the genes least tolerant of losing a copy. Missense variants: 411 observed, 425.62 expected, observed/expected ratio (o/e) 0.97, 90% interval 0.89 to 1.05. Synonymous variants: 172 observed, 153.52 expected, observed/expected ratio (o/e) 1.12, 90% interval 0.99 to 1.27.
Homologues: Orthologues: chimpanzee OTULINL (99% identical), macaque OTULINL (98% identical), pig OTULINL (90% identical), dog OTULINL (88% identical), rabbit OTULINL (88% identical), mouse Otulinl (84% identical), rat Otulinl (83% identical), guinea pig OTULINL (72% identical), tropical clawed frog otulinl (52% identical). Paralogues in human: OTULIN (33% identical).
Diseases named in the same sentence as OTULINL in open-access papers:
OTULINL is named in the same sentence as 6 diseases in open-access papers, as found by Europe PMC text mining. Sharing a sentence is not in itself a finding about the gene and the disease.
OTULINL shares sentences with these, for which no sentence is quoted: asthma (3 papers); allergic disease (1); cancer (1); glaucoma (1); Hyperglycemia (1); ovarian tumour (1).